PTPN22 (protein tyrosine phosphatase non-receptor type 22)
Diseases named in the same sentence as PTPN22 in open-access papers (continued):
Sharing a sentence is not in itself a finding about the gene and the disease.
cancer (39 papers, 2012 to 2026). A tumor composed of atypical neoplastic, often pleomorphic cells that invade other tissues. "As an example of a gene on a continuum from WT to LoF, PTPN22 shows an intermediate effect of gene expression for the hypomorphic cancer variant G100V." (PMID 38968069, 2024). "On the other hand, the same variant of PTPN22 was reported to augment antitumor responses and be associated with lower cancer incidence." (PMID 35634292, 2022). "Furthermore, evidence suggests that expression of the PTPN22 R620W variant is associated with enhanced responses to immune checkpoint therapies in human cancer patients." (PMID 38334623, 2024). "Addressing current therapy limitations is essential, especially considering that certain cancer patients with the rs2476601 variant exhibited enhanced responses to checkpoint inhibitor immunotherapy, highlighting PTPN22’s relevance as a druggable systemic target for cancer treatment." (PMID 39451542, 2024). "However, the identical variant of PTPN22 improves the anticancer defense and decreases cancer incidence." (PMID 37189748, 2023). "In addition, it was reported that the autoimmune susceptibility variant on PTPN22, which inhibits phosphatase activity, could improve cancer outcomes." (PMID 38796637, 2024). "Thus, the outcome of checkpoint inhibition therapy may depend on the PTPN22 allele expressed and the particular cancer under study." (PMID 33425916, 2020). "Inhibiting PTPN22 represents a promising cancer immunotherapeutic strategy, and our research offers proof of concept for the potential translatability of this target using a lead compound." (PMID 39451542, 2024). "Recent studies have underscored PTPN22’s role in cancer immunotherapy and its potential as a therapeutic target." (PMID 39451542, 2024). "Several studies have demonstrated that Ptpn22-/- mice have strong antitumor immune responses following implantation of syngeneic cancer cells." (PMID 39039893, 2024). "More recently, similar data were reported using chemically distinct PTPN22 inhibitors termed D14 and D34, adding to the evidence for the utility of targeting PTPN22 to improve cancer immunity." (PMID 38334623, 2024). "The role for PTPN22 in regulating T cell immune responses to infection have been less well studied, whilst recent data indicating a role for PTPN22 in modulating cancer immunity deserve further investigation." (PMID 39039893, 2024). "In CRC, the majority of important genes were found to be suppressed during tumor formation; however, PTPN22 expression increased at all stages, suggesting its involvement in cancer-related immunity." (PMID 37189748, 2023). "For example, PTPN22 was positively correlated with NETs in 7 cancer types with poor NET-related survival and in 1 cancer type with favorable NET-related survival." (PMID 35432310, 2022). "Targeting PTPN22 offers the potential to improve cancer immunotherapy using at least two clinically proven therapies and signaling pathways: IFNAR and TCR signaling pathways." (PMID 35154122, 2022). "The somatic mutations of the organoids were identified and cancer genes in the most relevant BC genes were also found, including ERBB4, HLA-DRB1, PDE4DIP, PTPN22." (PMID 32774159, 2020). "Targeting PTPN22 could afford the opportunity to augment cancer immunotherapy through at least two clinically validated classes of therapies and pathways—interferon alpha receptor (IFNAR) and T cell receptor (TCR) signaling." (PMID 39451542, 2024). "The pharmacological inhibition of PTPN22 may also represent a valid approach to improve anti-cancer immune responses." (PMID 38334623, 2024). "Several approaches have been used to address the question of whether PTPN22 can be targeted to enhance cancer immunotherapy." (PMID 38334623, 2024). "Therefore, the prospect of selectively inhibiting protein-tyrosine phosphatases (PTPs), including PTPN22, emerges as a promising therapeutic avenue across various human ailments, notably cancer." (PMID 39451542, 2024).
cancer (continued). "Studies have suggested that targeting inhibitory PTPN family proteins, including PTPN22, may also serve to boost anti-cancer immune responses and may be used in conjunction with established immune checkpoint blockade and ACT approaches." (PMID 39039893, 2024). "Therefore, balancing an enhanced capacity for effector responses with an increased propensity for exhaustion is a key concern for future targeting of PTPN22 in adoptive T cell cancer therapies." (PMID 38334623, 2024). "Recently, PTPN22 also emerged as a potential target for cancer immunotherapy." (PMID 35634292, 2022). "Stimulation by weak antigen are critical drivers of autoimmune and cancer responses, thus this function of PTPN22 may be highly relevant to the development of these diseases." (PMID 30483260, 2018). "However, recent studies suggest that under conditions of chronic stimulation, PTPN22-deficient effector CD8+ T cells can become exhausted and may function less well than wild-type T cells in anti-cancer responses." (PMID 38334623, 2024). "The CNV percentage in pan-cancer indicated that heterozygous amplification in cancers were widely found in genes PTPN1, PTPN7, PTPN12 and PTPN14 in most cancers, while heterozygous deletions were widely found in genes PTPN13, PTPN20, PTPN22 and PTPN23." (PMID 37884566, 2023). "Besides, the somatic mutations of the organoids were identified and cancer mutant genes in the most relevant BC genes were also found, including ERBB4, HLA-DRB1, PDE4DIP, PTPN22." (PMID 32774159, 2020). "As a result, PTPN22 and miR-1811 and miR-181b could serve as factors in designing therapies for T-ALL as well as biomarkers for diagnosis of this cancer." (PMID 30023329, 2018). "The transcriptional activity of the protein tyrosine phosphatase non-receptor type 22 (PTPN22) gene increased in all stages of the cancer, but the p-value was only less than 0.05 in CSIV vs. C. Forkhead box O1 (FOXO 1) and ubiquitin B (UBB) are statistically overexpressed in CSI." (PMID 38002011, 2023). "Increasing evidences have shown that dysregulation of PTPN22 offers the potential to improve cancer immunotherapy not only by regulating IFNAR and TCR signaling pathway, but also includes the activation of 3 inflammasomes through the regulation of autophagy and the pyrin domain of the NLR family." (PMID 35154122, 2022).
infection (19 papers, 2013 to 2024). The state of being infected such as from the introduction of a foreign agent such as serum, vaccine, antigenic substance or organism. "First, it was confirmed that individuals with PTPN22-C1858T polymorphism are predisposed to invasive infections with Streptococcus pneumoniae." (PMID 33717071, 2021). "While the PTPN22-C1858T polymorphism is irrelevant to higher susceptibility to the infection of M. tuberculosis in Caucasians and Asians, it is relevant to increased susceptibility to the infection of M. leprae." (PMID 33717071, 2021). "Carrying the PTPN22 rs2476601 risk allele A increased the odds 1.6-fold for developing infection-triggered ME/CFS." (PMID 32328064, 2020). "We show that mice deficient for PTPN22 are able to control the virus 30 days after infection, show reduced weight loss, and generate higher numbers of LCMV-specific CTLs and CD4 T cells with heightened function." (PMID 28747914, 2017). "A previous study from the same group demonstrated that Ptpn22-/- mice also clear LCMV-Clone 13 infection more efficiently than Ptpn22+/+ controls, with PTPN22-deficient CD4+ T cells retaining functional capacity and being less prone to exhaustion in chronic infection." (PMID 39039893, 2024). "Therefore, we set out to define how the Ptpn22 pro-autoimmune allele affected T cell populations during LCMV-cl13 infection." (PMID 38512979, 2024). "In addition to mycobacteria, a number of studies have focused on the relevance of PTPN22-C1858T polymorphism with raised susceptibility to infections by other bacteria." (PMID 33717071, 2021). "Specifically, there was enhanced anti-viral CD4 T cell function and improved CD8 T cell function late in infection, suggesting Ptpn22 contributes to the generation of T cell exhaustion." (PMID 38512979, 2024). "These researchers reported that PTPN22 R619W knock in mice had enhanced capacity to clear chronic lymphocytic choriomeningitis virus (LCMV-clone 13) infection as compared PTPN22 wild-type (WT) controls." (PMID 39039893, 2024). "Recent work identified PTPN22 itself as a target for the HIV Vpr protein during infection of primary human CD4+ T cells." (PMID 39039893, 2024). "Significant associations were identified between the SNPs PTPN22 rs2476601 and CTLA4 rs3087243 and ME/CFS, especially in patients who reported acute onset of disease after infection." (PMID 39044822, 2024). "Together, these findings clearly show that PTPN22 inhibits pro-inflammatory virus-specific CD4 T cell responses during LCMV Cl13 infection." (PMID 28747914, 2017). "For gene candidates, Vav3, Ptpn22, FcgR1 and S100a10, qPCR corroborated up-regulated expression found in susceptible AKR on day 35 post infection." (PMID 23442222, 2013). "Specific single nucleotide polymorphisms (SNPs), such as PTPN22 rs2476601 and CTLA4 rs3087243, are associated with infection-triggered CFS/ME, while other SNPs, such as IRF5 rs3807306 and TNF rs1799724, have decreased allele frequencies in CFS/ME patients who do not have infection-triggered onset." (PMID 39483544, 2024). "We found that lack of PTPN22 in mice resulted in viral clearance 30 days after infection, which was reflected in their reduced weight loss and overall improved health." (PMID 28747914, 2017). "Similarly, PTPN22 has been shown to be differentially expressed in chickens following pathogen challenge, and in particular following infection with Escherichia coli." (PMID 26819139, 2016). "Since Ptpn22 tempers TCR signaling, disrupting that regulatory mechanism, through presence of the allelic variant (PEP-619WW) may be what is driving this TFH increase during infection." (PMID 38512979, 2024). "Here, we examined the effects of PTPN22 on Tfh and germinal center (GC) responses after LCMV Cl13 infection." (PMID 28747914, 2017). "To analyze the effect of PTPN22 on T cell exhaustion and virus clearance in chronic LCMV Cl13 infection, we infected PTPN22+/+ and PTPN22−/− mice with 2 × 106 PFU LCMV Cl13." (PMID 28747914, 2017).
infection (continued). "At week 1 post infection CXCR4, FAS and PTPN22 showed higher expression in line L10H." (PMID 26819139, 2016). "Previously we and others found that, upon infection with LCMV-cl13, mice lacking Ptpn22 (PEP-null) have accelerated viral clearance and exhibit less of an exhausted T cell phenotype." (PMID 38512979, 2024). "Imperfect control of lymphocyte activity, due to SNPs of PTPN22, CTLA-4, BTLA, and some other elements of the immune response, makes it difficult to stop immune activity that is no longer needed after recovery from infection." (PMID 38792338, 2024).
hematologic disorder (3 papers, 2012 to 2018). A disease involving the hematopoietic system. "Analysis of known SLE risk loci identified a strong association between PTPN22 and the risk of hematologic disorder and with the development of antinuclear antibodies." (PMID 28619073, 2017). "In the present study, we have also identified and validated the association between SLE risk locus PTPN22 and the production of antinuclear antibodies and with the presence of a hematologic disorder." (PMID 28619073, 2017). "However, in the independent validation cohort, only the association between PTPN22 and hematologic disorder (PReplication = 0.043,PCombined = 8.25e-4) and between PTPN22 and the production of antinuclear antibodies (PReplication = 0.028,PCombined = 0.001) were significantly replicated." (PMID 28619073, 2017). "The expression of PTPN22 and miR-181 genes in all types of hematologic malignancies increases and is likely to contribute to the survival and death of cells by affecting a variety of signaling pathways." (PMID 30023329, 2018).
immune diseases (3 papers, 2014 to 2026). "Most studies on the association between immune disorders and PTPN22 showed an association with the 1858C/T rs2476601 polymorphism." (PMID 24816862, 2014). "The most likely pathway is related to activation and effector function of PTPN22 on T cells, so as to regulate and affect human immune diseases." (PMID 35692826, 2022).
bacterial infection (2 papers, 2021 to 2022). "Second, allogeneic hematopoietic stem cell transplant recipients have been found to have a significantly lower risk of post-transplantation bacterial infections after accepting corresponding allografts from PTPN22-C1858T polymorphic donors." (PMID 33717071, 2021).
infectious disease (2 papers, 2014 to 2017). A disorder directly resulting from the presence and activity of a microbial, viral, or parasitic agent in humans. "PTPN22-R620W constitutes a major “risk” allele for human autoimmune and infectious disease that may confer loss-of-function in anti-viral host defense." (PMID 28723925, 2017).
connective tissue diseases (1 paper, 2019). "Other SNPs of PTPN22 have been associated with connective tissue diseases." (PMID 30871019, 2019).
PTPN22 also shares sentences with these, for which no sentence is quoted: systemic sclerosis (7 papers); vasculitis (6); thyroid disease (5); pancreatic cancer (4); ulcerative colitis (4); ANCA associated vasculitis (3); Autoimmune Addison's disease (3); glioma (3); prostate carcinoma (3); age-related macular degeneration (2); autoimmune polyglandular syndrome (2); breast tumor (2); cardiovascular disease (2); chronic fatigue syndrome (2); combined immunodeficiency (2); genetic disease (2); Hirschsprung disease (2); hyperthyroidism (2); lupus erythematosus (2); metastatic tumors (2); pernicious anemia (2); Primary Sjögren’s Syndrome (2); rheumatic diseases (2); abdominal aortic aneurysm (1); adenocarcinoma (1); alopecia (1); Alzheimer disease (1); atrial fibrillation (1); autosomal recessive spastic paraplegia 47 (1); B-cell lymphomas (1).
A further 53 diseases each share a sentence with PTPN22 in 1 paper.